RND1 (Rho family GTPase 1)
Description:
Lacks intrinsic GTPase activity. Has a low affinity for GDP, and constitutively binds GTP. Controls rearrangements of the actin cytoskeleton. Induces the Rac-dependent neuritic process formation in part by disruption of the cortical actin filaments. Causes the formation of many neuritic processes from the cell body with disruption of the cortical actin filaments.
Synonyms: RHO6; ARHS; RHOS
Tractability: Small molecule: a structure with a bound ligand is known; it has a binding pocket of medium quality. Antibody: UniProt places it where antibodies can reach, with high confidence; its Gene Ontology location is reachable by antibodies, with high confidence; the Human Protein Atlas places it where antibodies can reach. PROTAC: ubiquitination databases record sites on it.
Gene: Protein-coding gene on chromosome 12 (48,857,145 to 48,865,870, reverse strand). Ensembl gene ENSG00000172602.
Subcellular location: Cell membrane; Cytoplasm, cytoskeleton
Subcellular location (Human Protein Atlas): Actin filaments; Plasma membrane; Vesicles
Pathways (Reactome):
Developmental Biology: SEMA3A-Plexin repulsion signaling by inhibiting Integrin adhesion; Sema4D induced cell migration and growth-cone collapse; Sema4D mediated inhibition of cell attachment and migration
Signal Transduction: RND1 GTPase cycle
Gene Ontology:
Molecular function: protein binding; signaling receptor binding; GTPase activity; protein kinase binding; G protein activity; GTP binding
Biological process: actin filament organization; negative regulation of cell adhesion; neuron remodeling; regulation of actin cytoskeleton organization; small GTPase-mediated signal transduction
Cellular component: actin cytoskeleton; adherens junction; plasma membrane; cytosol; cytoskeleton
Genetic constraint (gnomAD): Loss-of-function variants: 6 observed, 21.11 expected, observed/expected ratio (o/e) 0.28, 90% interval 0.16 to 0.56. The upper end of that interval is the gene's LOEUF score, 0.56, which puts it in group 2 of 6, group 1 being the genes least tolerant of losing a copy. Missense variants: 218 observed, 262.45 expected, observed/expected ratio (o/e) 0.83, 90% interval 0.74 to 0.93. Synonymous variants: 98 observed, 104.79 expected, observed/expected ratio (o/e) 0.94, 90% interval 0.79 to 1.11.
Homologues: Orthologues: macaque RND1 (99% identical), pig RND1 (98% identical), mouse Rnd1 (97% identical), guinea pig RND1 (96% identical), rabbit RND1 (96% identical), tropical clawed frog rnd1 (86% identical), dog RND1 (84% identical), zebrafish rnd1b (83% identical), zebrafish rnd1a (78% identical), rat Rnd1 (73% identical), chimpanzee RND1 (67% identical). Paralogues in human: RND3 (61% identical), RND2 (50% identical), RHOA (34% identical), RAC2 (34% identical), RHOC (34% identical), RAC1 (33% identical), RAC3 (33% identical), RHOBTB1 (33% identical), RHOQ (33% identical), CDC42 (32% identical), RHOJ (32% identical), RHOU (32% identical), and 10 more.
Diseases named in the same sentence as RND1 in open-access papers:
RND1 is named in the same sentence as 25 diseases in open-access papers, as found by Europe PMC text mining. Sharing a sentence is not in itself a finding about the gene and the disease. The quoted sentences say what the papers report.
glioblastoma (6 papers, 2018 to 2024). The most malignant astrocytic tumor (WHO grade IV). "Altogether, these results suggest that loss of RND1 in glioblastoma tumors could drive a mesenchymal subtype and hence, could decrease the overall survival in patients." (PMID 30333910, 2018). "The silencing of RND1 increases the in vitro migration and invasion of glioblastoma initiating cells and hepatocellular carcinoma cells." (PMID 31344837, 2019). "First, we analyzed RND1 expression by RT-qPCR in normal brain tissues, in several glioblastoma cell lines and in GSCs established in our laboratory." (PMID 30333910, 2018). "In silico analysis showed that low expression of RND1 constitutes a bad prognosis factor for glioblastoma patients." (PMID 30333910, 2018). "In conclusion, our study contributes to explain the shorter time to progression of patients with PVZ involvement and highlights RND1 as a gene involved in glioblastoma heterogeneity." (PMID 30333910, 2018). "Using the glioblastoma TCGA database, low levels of RND1 were also shown to correlate with a decreased overall survival of patients." (PMID 30333910, 2018). "RND1 induction was also observed in other human cell lines (glioblastoma U87, colon carcinoma HCT116, primary lung WI38 hTERT), and mouse cell lines (melanoma B16F10, embryonic NIH3T3) treated with CPT." (PMID 30209297, 2018). "In fact, RND1 expression is down-regulated in glioblastoma patients and in the most aggressive subtypes of breast cancers but it is up-regulated in esophageal squamous cell carcinoma." (PMID 30333910, 2018). "Based on functional enrichment of genes in glioblastoma patients, we identified six genes whose expression is inversely correlated to RND1 and that predict the survival of glioblastoma patients." (PMID 30333910, 2018). "RND1 has been described as a prognosis factor of survival for patients with an estrogen receptor negative breast cancer, with hepatocellular carcinoma or glioblastoma." (PMID 31344837, 2019). "Moreover, we demonstrated that low-expression of RND1 in glioblastoma patient samples was correlated with a worse prognosis for patients." (PMID 30333910, 2018). "RND1 expression is significantly down regulated in glioblastoma cells compared to normal tissues." (PMID 30333910, 2018). "Using TCGA database, we next examined whether this down-regulation of RND1 was related to the prognosis of glioblastoma patients." (PMID 30333910, 2018). "Additionally, transcriptomic analyses also revealed a down-regulation of RND1 in glioblastoma compared to normal brain." (PMID 30333910, 2018). "In consequence, targeting ITGA5 or MET genes could inhibit the invasive capacity of glioblastoma cells induced by low RND1 expression and especially the one of PVZ+ cells." (PMID 30333910, 2018). "To determine which signaling pathways controlled by RND1 might be involved in the prognosis of glioblastoma recurrence and thus survival, we performed a functional enrichment of genes." (PMID 30333910, 2018). "As loss of RND1 is involved in GSCs migration from PVZ+ tumors, known to be more aggressive than PVZ– tumors, we tested whether RND1 gene expression could be correlated with glioblastoma prognosis." (PMID 30333910, 2018). "We could hypothesize that misregulation of RND1 expression in glioblastoma cells leads to an optimal formation and turnover of focal adhesion sites and therefore, increased migration." (PMID 30333910, 2018). "Finally, based on signaling pathways activated in patients with low levels of RND1, we identified six genes that define an RND1low signature that is an independent prognostic factor in glioblastoma." (PMID 30333910, 2018). "Our functional enrichment of genes in patient tumors revealed that low expression of RND1 in glioblastoma induces an overexpression of focal adhesion proteins like extracellular matrix proteins (COL1A1 and LAMB1); integrins (ITGA5 and ITGB1); actin-binding proteins (FLNA; ACTN1) and vinculin." (PMID 30333910, 2018).
glioblastoma (continued). "In glioblastoma, we identified an RND1low signature of six genes (ITGA5, COL3A1, COL5A1, MET, COL1A2, LAMC1), upregulated in glioblastoma patients with low RND1, that predicts the overall survival of glioblastoma patients." (PMID 31344837, 2019). "In glioblastoma initiating cells, the expression of RND1 is inversely correlated with mesenchymal gene expression, such as TWIST1, SNAI1, and SNAI2, suggesting that RND1 blocks the mesenchymal phenotype." (PMID 31344837, 2019). "Finally, based on signaling pathways activated in patients with low levels of RND1, we identified an RND1low signature of six genes (MET, LAMC1, ITGA5, COL5A1, COL3A1, COL1A2) that is an independent prognostic factor in glioblastoma." (PMID 30333910, 2018). "This rapid induction of RND1 is also found in several non-tumorigenic cells, such as NIH3T3 fibroblasts, and in other tumor cells, such as U87 glioblastoma cells." (PMID 31344837, 2019).
breast carcinoma (5 papers, 2018 to 2024). "Although Ras/MAPK activating mutations are rare in breast cancer, they can occur infrequently, and we and others have previously reported loss of Ras/MAPK negative regulators (DUSP4, NF1, RND1) in breast cancer as a mechanism of pathway activation." (PMID 32634121, 2020). "In adenoid cystic carcinoma and in breast cancer, the deletion of RND1 gene concerns only one of the two alleles." (PMID 31344837, 2019). "In breast cancer, RND1 downregulation facilitates tumor occurrence and EMT through Ras‐MAPK signaling." (PMID 39129202, 2024). "RND1 level is suppressed in highly invasive breast cancer, hepatocellular carcinoma, and high‐grade glioma, and it exhibits tumor‐repressive effects." (PMID 39129202, 2024). "The 12q12-q13 region where RND1 gene is located is deleted in several cancers, such as pancreas cancer, adenoid cystic carcinoma, and breast cancer." (PMID 31344837, 2019). "On the contrary, the re-introduction of RND1 gene in mammary tumor cells slows down the tumor growth." (PMID 31344837, 2019). "Consistent with our present data, inactivation of RND1 induces the invasion of immortalized breast cells in 3D matrigel and, overexpression of RND1 diminishes lung colonization in mice xenografted with breast cancer cells." (PMID 30333910, 2018). "In breast cancer, Oct4 can bind to the RND1 promoter and restrain its transcription." (PMID 39129202, 2024). "Moreover, in breast cancers, the Polycomb Repressor Complex 2 is involved in the inhibition of RND1 gene expression." (PMID 31344837, 2019). "RND1 is down-regulated in the most aggressive subtypes of breast cancers (estrogen receptor negative, triple negative, and basal), in hepatocellular carcinoma and in high grade glioma." (PMID 31344837, 2019).
hepatocellular carcinoma (5 papers, 2018 to 2024). A malignant tumor that arises from hepatocytes. "The role of RND1 in EMT has been extended to hepatocellular carcinoma cells, in which the depletion of RND1 also causes EMT, this time via the activation of RHOA." (PMID 31344837, 2019). "The depletion of RND1 induces hepatocellular carcinoma proliferation, whereas it decreases esophageal squamous cell carcinoma proliferation." (PMID 31344837, 2019). "In hepatocellular carcinoma cells, the increase of invasion induced by RND1 depletion is mediated by the activation of RHOA." (PMID 31344837, 2019). "However, the role of Rnd1 in hepatocellular carcinoma (HCC) progression remains unclear." (PMID 29706627, 2018).
glioma (4 papers, 2015 to 2024). A benign or malignant brain and spinal cord tumor that arises from glial cells (astrocytes, oligodendrocytes, ependymal cells). "In summary, our study demonstrated that high RND1 expression level was associated with a lower malignancy in gliomas and a favourable prognosis for patients with GBM." (PMID 35505371, 2022). "Therefore, in the future, we must examine whether EMT caused by RND1 might improve the sensitivity of gliomas to ferroptosis." (PMID 35505371, 2022). "We observed that RND1 influenced the glioma cell growth in a ferroptosis-dependent manner when GBM cell lines U87 and A172 were treated with Ferrostatin-1 or Erastin." (PMID 35505371, 2022). "RND1 markedly inhibited glioma growth in vitro, as evaluated by cell viability assays and colony formation assays." (PMID 35505371, 2022). "We first analyzed RND1 expression in glioma samples obtained from public databases and collected clinical samples." (PMID 35505371, 2022). "We searched TCGA database to analyze RND1 expression in gliomas and found that RND1 mRNA level was down-regulated in GBM tissue compared to normal brain tissue and that RND1 expression decreased with increasing glioma grade." (PMID 35505371, 2022). "To study the intrinsic effect of RND1 on the inhibition of glioma growth, we used Z-VAD-FMK, necrosulfonamide, and Ferrostatin-1 to reverse apoptosis, necrosis, and ferroptosis in glioma cells, respectively." (PMID 35505371, 2022). "As RhoGTPases are known regulators of cell migration and have been recently demonstrated as key elements of glioma pathogenesis, we focused our study on the role of RND1 in GSC migration." (PMID 30333910, 2018). "Notably, a study on glioma stem-like cells (GSCs) demonstrated that RND1 regulated the invasion of GSCs in the periventricular zone." (PMID 35505371, 2022). "The role of RND1 in GBM was unknown until a study in 2018 demonstrated that glioma stem-like cells in the periventricular zone possess higher invasive capacities regulated by RND1." (PMID 35505371, 2022). "TCGA database analysis revealed that RND1 expression levels were significantly lower in GBM than in normal brain tissue and that RND1 expression was negatively correlated with glioma grade." (PMID 35505371, 2022). "RND1 inhibited the level of GSH and induced lip ROS in glioma cells." (PMID 35505371, 2022). "Thus, RND1 predicted a better prognosis for patients with GBM and probably acted as a tumor suppressor gene in glioma." (PMID 35505371, 2022). "Seven Rho GTPases (RND1, RND3, RAC3, RHOA, RAC2, RAC1 and RHOC) showed a significantly greater connectivity in grade IV glioma and seven (CHP, RHOD, RHOF, RHOB, RHOQ, RND2, RHOBTB3) showed greater connectivity in grade II glioma." (PMID 26132659, 2015).
esophageal squamous cell carcinoma (3 papers, 2018 to 2024). Esophageal squamous cell carcinoma (ESCC) is a type of esophageal carcinoma (EC) that can affect any part of the esophagus, but is usually located in the upper or middle third. "In contrast, RND1 is upregulated in low‐grade breast tumors, gastric cancer cell lines, and esophageal squamous cell carcinoma." (PMID 39129202, 2024). "By contrast, RND1 transcripts are up-regulated in low grades of breast tumors, in gastric cancer cell lines, and in esophageal squamous cell carcinoma." (PMID 31344837, 2019). "However, data from esophageal squamous cell carcinoma refute the idea that RND1 would be a universal tumor suppressor gene." (PMID 31344837, 2019).
breast tumors (2 papers, 2019 to 2024). "The impact on RND1 function of four missense mutations discovered in breast tumors has been studied." (PMID 31344837, 2019).
gastric cancer (2 papers, 2019 to 2024). A primary or metastatic malignant neoplasm involving the stomach. "Inhibition of AGAP2-AS1 expression with siRNA increases RND1 mRNA in non-small lung cancer H1975 cells and gastric cancer BGC823 cells." (PMID 31344837, 2019).
melanoma (2 papers, 2017 to 2018). A malignant, usually aggressive tumor composed of atypical, neoplastic melanocytes. "Rnd1 had significantly higher expression in melanoma cells than in MC." (PMID 28404912, 2017).
Stroke (2 papers, 2012 to 2020). Sudden impairment of blood flow to a part of the brain due to occlusion or rupture of an artery to the brain. "In stroke subjects, frontal, temporal and parietal lobe volumes were significantly smaller on the stroke side as compared to the non-stroke side, and to the RND1 and RND2 sides of non-stroke subjects." (PMID 23071639, 2012).
viral infections (2 papers, 2021 to 2022). "As Rnd1 expression is induced during bacterial and viral infection, we tested its role during bacterial and viral infection." (PMID 35654795, 2022). "We show that Rnd1 does not just antagonise viral infection but also bacterial infections, although through two different molecular mechanisms." (PMID 35654795, 2022). "We compared publicly available human and bat transcriptomic data in the basal state and after virus infection and found that a gene Rnd1 that is not characterised as antiviral is induced more than 200 folds in bat cell lines but not in humans." (PMID 35654795, 2022). "Furthermore, RND1 is upregulated in infected HIBCPP cells, which plays roles during cell adhesion, modulation of the actin cytoskeleton, and viral infections." (PMID 34863201, 2021).
bladder pain syndrome (1 paper, 2014). "Thus miR-199a-5p is expressed in the bladder's smooth muscle and urothelium and may play a role in bladder pain syndrome by suppressing LIN7C, ARHGAP12, PALS1, RND1 and PVRL1." (PMID 24574962, 2014).
esophageal carcinoma (1 paper, 2018). A primary or metastatic malignant neoplasm involving the esophagus. "On the contrary, overexpression of RND1 in esophageal carcinoma cells promotes their migration." (PMID 30333910, 2018).
Lung Squamous Cell Carcinoma (1 paper, 2024). "FOXA2 activates RND1 to suppress the arachidonic acid metabolism pathway and cisplatin resistance in lung squamous cell carcinoma." (PMID 39129202, 2024). "We used the lung squamous cell carcinoma (LUSC) mRNA data set to explore the differentially expressed gene (RND1) in LUSC and detected RND1 expression in LUSC cells and DDP‐resistant cells by qRT‐PCR." (PMID 39129202, 2024).
osteosarcoma (1 paper, 2019). A usually aggressive malignant bone-forming mesenchymal neoplasm, predominantly affecting adolescents and young adults. "The induction of RND1 protects osteosarcoma cells against camptothecin, likely by inhibiting apoptosis." (PMID 31344837, 2019). "Using a RT-qPCR screen of Rho GTPase expression in response to the topoisomerase I inhibitor camptothecin, we identified RND1 as a Rho GTPase gene, which is rapidly induced in the osteosarcoma U2OS cell line." (PMID 31344837, 2019).
prostate carcinoma (1 paper, 2011). A carcinoma that arises from epithelial cells of the prostate gland. "We found that a series of Plexin-B1 mutations in the hydrophobic interface, Trp1807GluPlex, Leu1815ProPlex (previously linked to prostate cancer), and Leu1815GluPlex, completely abolished its interactions with Rac1* and Rnd1." (PMID 21912513, 2011).